IGF1 (insulin like growth factor 1)
Diseases named in the same sentence as IGF1 in open-access papers (continued):
Sharing a sentence is not in itself a finding about the gene and the disease.
benign prostatic hyperplasia (19 papers, 1997 to 2026). A non-cancerous nodular enlargement of the prostate gland. "Overexpression of IL-8 and IL- 6 are associated with increased production of growth stimulating factors, FGF and IGF-1 and thereby induce prostate hyperplasia." (PMID 38082261, 2023). "The aim of this study was to investigate the protective effect of metformin against experimentally-induced prostatic hyperplasia in rats with emphasis on its potential effects on certain key players of IGF-1/IGF-1R signaling pathway." (PMID 26492952, 2015). "Induction of prostatic hyperplasia in our model is accompanied with significant increase of the clusterin and IGF-1 expression in ventral lobe of rat prostate, while the TGF-β1 expression was significantly decreased." (PMID 22195697, 2011). "Therefore, the aim of the current study was to investigate the protective effect of metformin against experimentally-induced prostatic hyperplasia in rats with emphasis on role of IGF-1/IGF-1R cascade." (PMID 26492952, 2015). "Also, androgen treatment induced prostatic hyperplasia in-vivo is dependent on increased expression of growth factors mainly IGF-1 and IGF-1R21 and increased expression of phosphorylated Akt as well as Bcl-222." (PMID 26492952, 2015). "Furthermore, capsaicin treatment downregulated IGF-1 expression, suggesting its potential role in modulating IGF-1 signalling involved in cellular proliferation and differentiation and reversing prostate hyperplasia." (PMID 41987603, 2026). "Serum concentrations of prolactin (PRL), insulin‐like growth factor‐1 (IGF‐1) and 25 hydroxyvitamin D3 (25‐OHD3) were analysed to investigate their possible involvement in the pathogenesis of benign prostatic hyperplasia (BPH)." (PMID 34015193, 2021).
infarction (19 papers, 2012 to 2024). A localised pathological necrosis of tissue resulting from obstruction of the blood supply usually by a thrombus, an embolus, or vascular torsion. "The rapid release of IGF-1 could provide an immediate signal for cell survival to reduce cell loss by apoptosis due to infarction and thus safeguard the remaining functional myocardium." (PMID 36145603, 2022). "Four of eight asphyxia-vehicle foetuses and one of four asphyxia-IGF-1 foetuses developed infarcts in lateral white matter at 35 days post-occlusion (Fisher exact, P = 0.58)." (PMID 39507274, 2024). "After infarction, cTnI was significantly higher in IGF-1 MSPs than in CON (p = 0.009) and MSPs (p = 0.019) (One-way ANOVA, post-hoc Bonferroni test)." (PMID 32346015, 2020). "Several lines of evidence point toward a key role of the growth hormone/insulin-like growth factor-1 axis in the pathophysiology of post-infarction structural and electrophysiologic remodeling." (PMID 32019245, 2020). "In a pig model, a single, low-dose of IGF-1 administered locally after acute MI showed long-term benefits in infarction size as well as cardiac wall structure and function." (PMID 29881402, 2018). "From these findings, we speculated that SeP promotes I/R-induced infarction through the impairment of IGF-1 signaling in the heart." (PMID 29547524, 2018). "A significant percentage of implanted CPC actively proliferated and migrated from the cell sheet to the site of infarction that could probably be caused by increasing production of growth factors and cytokines in a damaged ischemic myocardium (SDF-1, HGF, VEGF, and IGF-1)." (PMID 30046593, 2018). "Our main aim was to test the effect of sustained IGF-1 and HGF co-administration in an in vivo porcine infarction model." (PMID 27423905, 2016).
non-alcoholic fatty liver disease (19 papers, 2011 to 2025). "So, IGF-1, leptin, and adiponectin are considered non-invasive biomarkers for non-alcoholic fatty liver diseases (NAFLD) diagnosis." (PMID 36991247, 2023). "An increasing body of research indicates that IGF1 directly targets the liver, as well as hepatocytes, macrophages, and hematopoietic stem cells, through a variety of mechanisms that inhibit the progression of nonalcoholic fatty liver disease." (PMID 38469144, 2024). "Likewise, IGF-1 and IGFBPs are involved in the pathophysiology of Non-Alcoholic Fatty Liver Disease (NAFLD) and in the regulation of glucose homeostasis." (PMID 35457175, 2022). "IGF-1 is used as a marker of medical conditions and diseases, such as acromegaly, breast cancer, prostate cancer, type 1 and type 2 diabetes (T2DM), heart disease, non-alcoholic fatty liver disease (NAFLD) and sepsis." (PMID 34650980, 2021). "In non-alcoholic fatty liver disease (NAFLD) and advanced fibrosis, it was shown that the levels of GH, IGF-1, and IGFBP-3 varied according to the severity of the steatosis, which differed from the variation in samples taken from patients with hepatitis C virus-related CLD." (PMID 29487568, 2018).
thyroid nodule (19 papers, 2013 to 2026). A small circumscribed mass in the THYROID GLAND that can be of neoplastic growth or non-neoplastic abnormality. "In contrast, the AUC for the combined model incorporating IGF-1, IGFBP-3, and the IGF-1/IGFBP-3 molar ratio demonstrated a significant association with the presence of thyroid nodules in T2DM patients (AUC = 0.619, P < 0.001)." (PMID 39444449, 2024). "It needs more studies with more subjects to evaluate the effects of IGF-1/IGFBP-3 levels on thyroid nodules and the risk of thyroid malignancy." (PMID 29081797, 2017). "Therefore, we speculated that there may be some associations between serum 25(OH)D3 and IGF-1 in the formation of thyroid nodules." (PMID 31077177, 2019). "Additional clinical features included labial lentigines, multiple cutaneous myxomas, thyroid nodules, mammary microcalcifications, elevated serum levels of growth hormone and insulin-like growth factor 1 (IGF-1), and a recurrent left atrial myxoma." (PMID 40641912, 2025). "The ROC curve analysis evaluated the potential of serum IGF-1, IGFBP-3, and the IGF-1/IGFBP-3 molar ratio as predictors of thyroid nodules in patients with T2DM." (PMID 39444449, 2024). "The results indicated that IGF-1, IGFBP-3, and the IGF-1/IGFBP-3 ratio individually exhibited an uncertain predictive value for thyroid nodules in patients with T2DM (AUC=0.527, AUC=0.501, AUC=0.504, P>0.05)." (PMID 39444449, 2024). "Kimura showed that insulin-like growth factor (IGF-1) can stimulate the proliferation and differentiation of thyroid cells, which partially explains the high prevalence of thyroid nodules in diabetic patients." (PMID 32148489, 2020). "IGF-1 probably plays an important role in the genesis and development of certain solid cold thyroid nodules, including papillary thyroid carcinomas, nodular goiters, and follicular adenomas." (PMID 31077177, 2019). "This study aimes to clarify the changes and interactions of serum 25(OH)D3 and IGF-1 levels in thyroid nodules patients." (PMID 31077177, 2019). "The present study aimed to study the relationship between serum 25 hydroxyvitamin D3(25(OH)D3) and insulin-like growth factor-1 (IGF-1) and thyroid nodules." (PMID 31077177, 2019). "At present, there are relatively few reports concerning the relationship between serum 25(OH)D3, IGF-1, and thyroid nodules, however, similar reports have been found in some other diseases as well." (PMID 31077177, 2019). "Insulin-like growth factor-1 (IGF-1) has been implicated in tumor cell apoptosis, transformation, invasion, and metastasis; however, its role in thyroid nodules is undetermined." (PMID 29081797, 2017). "It was supposed that the role of insulin in promoting the formation of thyroid nodule may be partially mediated by the proliferation effective of IGF-1." (PMID 34550096, 2021). "LRA showed that serum 25(OH)D3 and IGF-1 were positively correlated with thyroid nodules." (PMID 31077177, 2019). "There was a positive correlation between IGF-1 and serum 25(OH)D3 in thyroid nodules (P < 0.05)." (PMID 31077177, 2019). "Similarly, all the subjects were divided into four groups according to the four digits of serum IGF-1, then the incidence of thyroid nodules was reduced in Q1 group to Q4 group." (PMID 31077177, 2019). "Serum IGF-1 can be one of the indirect protective factors for thyroid nodules as well." (PMID 31077177, 2019). "The literature results about the relation between IGF-1 and thyroid nodule size were controversial." (PMID 29081797, 2017). "According to our results, we suggested that a higher IGF-1 level in multinodular cases as well as an increase in IGFBP-3 level that was parallel to an increase in thyroid nodule size were the findings suggesting the role of IGF-1 and IGFBP-3 in the pathogenesis of nodular goiter." (PMID 29081797, 2017). "Therefore, it is speculated that these factors may affect the relationship between serum IGF-1 and the incidence of thyroid nodules." (PMID 31077177, 2019).
thyroid nodule (continued). "Serum IGF-1 may be as one of the indirect protective factors for thyroid nodules as well." (PMID 31077177, 2019). "The results of this study suggest that serum 25(OH)D3 is a protective effect of thyroid nodules, and IGF-1 may affect the occurrence of thyroid nodules by 25(OH)D3, meanwhile serum IGF-1 may be as one of the indirect protective factors for thyroid nodules,which needs further study." (PMID 31077177, 2019). "Therefore, we speculated that IGF-1 may be involved in the pathophysiological process of thyroid nodules along with 25(OH)D3 and FBG, however, further studies are required to confirm that finding." (PMID 31077177, 2019). "The correlation of serum 25(OH)D3 with age, IGF-1, FBG, blood lipid, FINS, thyroid function, liver function, and cross sectional area of thyroid nodules was analyzed by Spearman’s correlation analysis." (PMID 31077177, 2019). "This study demonstrated the possible role of both IGF-1 and IGFBP-3 in the growth and the formation of multinodularity of thyroid nodules." (PMID 29081797, 2017). "IGF-1 concentrations at last follow-up were not different in patients with thyroid nodules (226.3±144.8 ng/mL) compared to patients without thyroid abnormalities (239.7±139.6 ng/mL) (p = 0.7)." (PMID 25127456, 2014). "With current guidelines generally advising against routine ultrasound screening for thyroid nodules in the general population, a combined predictive approach using IGF-1, IGFBP-3, and the IGF-1/IGFBP-3 ratio might hold promise for preventing thyroid nodules in T2DM patients." (PMID 39444449, 2024). "To date, the relationship between serum IGF-1 level and thyroid nodule is not still clear." (PMID 31077177, 2019). "Locally determined GH and IGF-1 in each participating center may influence the correlation studies, but not the results referring to thyroid nodules and cancer prevalence." (PMID 25127456, 2014).
esophageal cancer (18 papers, 2006 to 2025). A primary or metastatic malignant neoplasm involving the esophagus. "By improving these metabolic parameters, GLP-1 RAs reduce the concentrations of insulin-like growth factor (IGF) binding protein, resulting in lower levels of free IGF-1 in cells and tissues, indirectly reduce the risk of esophageal cancer." (PMID 40182628, 2025). "It was also shown that physical activity reduces fasting insulin C-peptide and IGF-1, as well as lowering inflammatory cytokines, and increases adiponectin, reducing the risk of gastric and esophageal cancers." (PMID 39766104, 2024). "Cancers of the oesophagus, mouth and pharynx were significantly associated with lower levels of IGF-1 and cancer of the lymphoma was significantly associated with lower levels of IGF-2." (PMID 16804529, 2006). "Additionally, IGF-1 is implicated in promoting the proliferation of esophageal cancer cells, as well as contributing to their drug resistance." (PMID 38413558, 2024). "Concurrently, some reports also confirmed the high expression of IGF-1R in ESCC and the promotion of proliferation and drug resistance of IGF-1 in esophageal cancer cells." (PMID 38413558, 2024). "Meanwhile, the addition of PI3K/Akt pathway activator IGF1 enhanced the proliferation of esophageal cancer cells and suppress the weaker effect induced by HMGB1 depression." (PMID 36260180, 2022). "But the addition of IGF1 weak the effect of HMGB1 depression on apoptosis increasing of esophageal cancer cells." (PMID 36260180, 2022). "Serum IGF-1 level correlates with pathological stage, depth of invasion and prognosis in esophageal cancer patients." (PMID 26317790, 2015). "The insulin growth factor-1 (IGF1) and IGF1 receptor (IGF1R) signaling pathway, implicated in esophageal cancer growth and progression, has been shown to play pivotal roles in cell growth, differentiation, survival, transformation and metastasis." (PMID 26317790, 2015). "In addition, we inhibited the PI3K/Akt pathway with ly294002 and activated it with IGF1, then we explored the invasion, proliferation ability, and apoptosis of esophageal cancer cells in vitro by transwell, CCK8 assay, and flow cytometry respectively." (PMID 36260180, 2022). "Recent studies have also further highlighted the potential central role of Akt in Barrett’s oesophageal cancer progression: signalling via the insulin/insulin-like growth factor-1 axis and HER2 receptor also activates Akt along the Barrett’s dysplasia-cancer sequence." (PMID 33582946, 2021). "Therefore, this study is conducted to investigate the mechanism of C-erbB-2 silencing and IGF-1 pathway on esophageal carcinoma (EC) cell biological behaviors." (PMID 34233689, 2021). "Increased levels of IGF-1 and IGF-2 are associated with many cancers, including esophageal cancer." (PMID 32041673, 2020). "CK2 may be mediating inhibition of 5-fluorouracil (5-Fu)-induced apoptosis by IGF-1 in esophageal carcinoma cells." (PMID 28134850, 2017). "This study aimed to explore the causal relationship between concentrations of various insulin-like growth factors (IGFs) and IGF-binding proteins (IGFBPs) and esophageal cancer (ESC), addressing the gap in understanding the genetic link between IGF1 and ESC." (PMID 39969361, 2024). "However, certain chemotherapeutic agents, such as cisplatin, one of the commonly used drugs in chemotherapy for esophageal cancer, can reduce IGF-1 protein levels by approximately 85% and inhibit IGF-1/PI3K/Akt signaling in skeletal muscle." (PMID 38267975, 2024).
lung adenocarcinoma (18 papers, 2010 to 2024). A carcinoma that arises from the lung and is characterized by the presence of malignant glandular epithelial cells. "In Kras-driven lung adenocarcinoma mouse model, loss of Ezh2 release the insulin-like growth factor 1 (Igf1), further amplify the activation of Akt-ERK signaling and promote tumor formation." (PMID 36263120, 2022). "The current study explored the oncogenic role of PHF5A in the pathogenesis of lung adenocarcinoma via the regulation of numerous signaling pathways including IGF-1." (PMID 37483794, 2023). "In lung adenocarcinoma, loss of function of EZH2 was observed to increase the number of tumor lesions, which was attributed to activation of AKT and ERK through insulin-like growth factor 1 (IGF1) signaling." (PMID 38036730, 2023). "Higher glucose levels and the IGF1R/IGF1 axis promote tumor development, inhibit tumor cell death and activate glucose metabolism in human lung adenocarcinoma cells." (PMID 35574343, 2022). "In lung adenocarcinoma cell lines, Trop2 interacts with insulin-like growth factor 1 (IGF-1) and prevents its binding to the IGF-1R." (PMID 33187148, 2020). "In contrast, overexpression of SOCS2 in IGF1-treated lung adenocarcinoma cells markedly decreased the migratory and invasive abilities as assessed by the wound healing and transwell assays." (PMID 29559623, 2018). "Earlier studies postulate that IGF-1-induced lung adenocarcinoma through activation of MAPK- and AKT-signaling pathways." (PMID 28240047, 2017). "Growth factor signaling may affect the catalytic activity of PKM2, inducing its nuclear translocation, as we previously demonstrated in treating a human lung adenocarcinoma cell line with insulin-like growth factor 1 (IGF-1)." (PMID 39769402, 2024). "Most interestingly, the expression of SOCS2 dose dependently reduced the interaction between IGF1R and STAT3 or STAT5, indicating that SOCS2 acts as a STAT3/STAT5 inhibitor that can competitively bind to IGF1R and thus can attenuate the IGF1-induced STAT3/STAT5 activity in lung adenocarcinoma cells." (PMID 29559623, 2018). "Finally, we observed that higher IGF-1 expression is an indicator of poor prognosis among lung adenocarcinoma patients." (PMID 29255466, 2017). "TP53INP1, IGF1 and ZMAT3 were differentially expressed in clinical samples of lung adenocarcinoma with BM, while miR-106a and TP53INP1 showed a significant negative correlation." (PMID 34718338, 2021). "In the current study, our data show that SOCS2 is involved in attenuating the IGF1-induced STAT3 and STAT5 activity in lung adenocarcinoma cells." (PMID 29559623, 2018). "Further functional studies indicated that insulin-like growth factor 1 (IGF1)-driven migratory and invasive behaviours of lung adenocarcinoma cells can be partially suppressed by exogenous SOCS2 expression." (PMID 29559623, 2018). "Fenofibrate also significantly reduced the serum insulin and insulin-like growth factor (IGF)-1 levels, and decreased the immunohistochemical expression of IGF-1 receptor (IGF-1R), phosphorylated Akt, and phosphorylated Erk1/2 in lung adenocarcinomas." (PMID 24857924, 2014). "The data show that IGF-1 reduces the activity of PKM2 in ARPE-19 cells, consistent with our previous observations in a human lung adenocarcinoma cell line, suggesting that activation of IGF1R signaling is associated with a decreased activity of the pyruvate kinase enzyme across multiple cell types." (PMID 39769402, 2024). "PHF5A participates well in progression of different types of cancers including breast, lung, hepatocellular, lung adenocarcinoma and gastric tumors occurs through regulation/stimulation of numerous signaling pathways such as AKT/mTOR, NF- κB, IGF-1 and YAP signaling pathways." (PMID 37483794, 2023).
lung adenocarcinoma (continued). "In conclusion, this study presents the pivotal finding that low expression of SOCS2 induces invasion and metastasis of human lung adenocarcinoma cells by regulating EMT both in vitro and in vivo, which is mainly dependent on the IGF1/IGF1R-stimulated STAT3 or STAT5 pathway." (PMID 29559623, 2018). "Since IGF1 signalling confers the EMT to several types of cancer cells, we further examined whether SOCS2 is involved in the IGF1-induced EMT process of lung adenocarcinoma cells." (PMID 29559623, 2018). "Moreover, IGF1 could not effectively induce EMT and tumour malignant development in SOCS2-overexpressed lung adenocarcinoma cells, further indicating the critical inhibitory role of SOCS2 in the IGF1/IGF1R axis in the EMT and progression of lung adenocarcinoma cells." (PMID 29559623, 2018). "Therefore, IGF-1 could be a negative prognostic factor in lung adenocarcinoma patients." (PMID 29255466, 2017). "Furthermore, IGF1 treatment could not effectively decrease E-cadherin protein levels and increase the expression of mesenchymal markers in A549-SOCS2 and SPC-A1-SOCS2 cells, indicating that SOCS2 is involved in the regulation of IGF1-induced EMT in lung adenocarcinoma cells." (PMID 29559623, 2018).